ALDH3A1 (aldehyde dehydrogenase 3 family member A1)
Diseases named in the same sentence as ALDH3A1 in open-access papers (continued):
Sharing a sentence is not in itself a finding about the gene and the disease.
non-small cell lung carcinoma (9 papers, 2008 to 2025). A group of at least three distinct histological types of lung cancer, including non-small cell squamous cell carcinoma, adenocarcinoma, and large cell carcinoma. "In non-small cell lung carcinoma, hypoxia-induced ALDH3A1 expression suppresses oxidative phosphorylation and promotes cell proliferation." (PMID 40529228, 2025). "Aldehyde dehydrogenase isozymes ALDH1A1 and ALDH3A1 are highly expressed in non small cell lung cancer." (PMID 19025616, 2008). "Previous studies have confirmed that ALDH3A1 can enhance glycolysis in non-small-cell lung cancer." (PMID 41327788, 2025). "The expression of ALDH3A1 in non-small cell lung cancer is high." (PMID 36814901, 2023). "In addition, Aldh3a1 is highly expressed in non-small cell lung cancer (adenocarcinoma and squamous cell carcinoma) and in tobacco smokers versus nonsmokers." (PMID 36539822, 2022). "In the non-small cell lung cancer model the following 5 DEPs were found to be involved in the GSH metabolism pathway (G6PD, PRDX2, IDH1, MGST1 and 6PGD), 4 DEPs in the PPP pathway (G6PD, TALDO1, TKT and 6PGD) and 1 DEP involved in the glycolysis pathway (ALDH3A1)." (PMID 28303926, 2017).
pancreatic cancer (9 papers, 2016 to 2025). "Similarly, high ALDH3A1 expression has been linked to chemoresistance in paclitaxel plus gemcitabine-resistant pancreatic cancer cells, possibly by modulating intracellular oxidative stress levels." (PMID 40868269, 2025). "The expression of ALDH1A1 and ALDH3A1 has also been linked to NRF2 in pancreatic cancer cells." (PMID 34207383, 2021). "Immunohistochemical analysis demonstrated high expression of ALDH3A1 in pancreatic cancer cells of human tumor tissues compared to normal pancreatic tissues." (PMID 40868269, 2025). "Our data showed that pancreatic cancer with low ALDH3A1 expression was predicted to be more sensitive to paclitaxel." (PMID 40868269, 2025). "Immunohistochemical staining and single-cell sequencing consistently revealed high ALDH3A1 expression in pancreatic cancer, with localization predominantly in cancer cells within the tumor microenvironment." (PMID 40868269, 2025). "ALDH3A1 is also upregulated in pancreatic cancer tissues, where it plays a crucial role in tumor progression and immune suppression." (PMID 40529228, 2025). "High expression of ALDH1L1, ALDH3A1, and ALDH3B1 was associated with shorter overall survival, while ALDH5A1 expression was associated with longer overall survival of pancreatic cancer patients." (PMID 40868269, 2025). "ALDH3A1 expression was substantially higher in human pancreatic tumors than in the normal pancreas by immunohistochemistry." (PMID 40868269, 2025). "The Nrf2 inducer DEM increased aldh3a1 expression in KPC mouse-derived pancreatic cancer cell lines, which was lost in Nrf2-null cell lines." (PMID 35053572, 2022). "Of importance, NRF2-KD reduces the expression of CSC markers, such as ALDH1A1 and ALDH3A1, in pancreatic cancer cells." (PMID 34207383, 2021). "NRF2-KD abolished the expression of ALDH1A1 and ALDH3A1, leading to sensitization of pancreatic cancer cells to 5-fluorouracil (5-FU)." (PMID 34207383, 2021). "Aldehyde dehydrogenase 1 family, member A1 (ALDH1A1) and aldehyde dehydrogenase 3 family, member A1 (ALDH3A1) have been identified as a biomarker for cancer stem-like cells including pancreatic cancer stem-like cells." (PMID 28671577, 2017). "HIPK3 has been related to apoptosis resistance, CBR1 has been identified as a patient survival marker, ALDH3A1 and ALDH3A2 have been related to drug response, and NOS1 has been related to pancreatic cancer risk." (PMID 29285214, 2017). "To evaluate the important role of NRF2 in regulation of the expression of ALDH1A1 and ALDH3A1 in pancreatic cancer cells, we first knocked down the expression of NRF2 in pancreatic cancer AsPC-1, COLO-357 and PANC-1 cells using siRNA." (PMID 28671577, 2017). "The RT-PCR results demonstrated that the mRNA of ALDH1A1 and ALDH3A1 were significantly decreased in NRF2-siRNA transfected pancreatic cancer cells compared to those in control-siRNA transfected cells." (PMID 28671577, 2017). "Single-cell analysis shows that ALDH3A1 is mainly expressed in pancreatic cancer cells." (PMID 40868269, 2025). "In a study that tested the combined administration of halofuginone and gemcitabine in pancreatic cancer, halofuginone administration sensitized KPC mouse-derived pancreatic cancer cell lines to gemcitabine in vitro and in vivo, along with reduction of aldehyde dehydrogenase 3a1 (Aldh3a1)." (PMID 35053572, 2022). "The results indicate that ALDH3A1 may contribute to chemoresistance in pancreatic cancer." (PMID 40868269, 2025). "ALDH3A1 and ALDH3B1 were found to be upregulated and ALDH1L1 downregulated in pancreatic cancer versus normal tissues." (PMID 40868269, 2025). "In this study comprehensively analyzed ALDHs in PAAD and identified four genes (ALDH1L1, ALDH3A1, ALDH3B1, ALDH5A1) as prognostic indicators for pancreatic cancer." (PMID 40868269, 2025). "Based on survival analysis, 6 out of 32 MMRGs (LDHA, ALDH3B1, LDHAL6B, PKM, ALDH3A1, and PGAM4) in pancreatic cancer were of survival significance." (PMID 36814901, 2023).
pancreatic cancer (continued). "ALDH1L1, ALDH3A1, ALDH3B1, and ALDH5A1 may serve as potential prognostic markers and predictors of chemotherapy response in pancreatic cancer patients." (PMID 40868269, 2025).
gastric cancer (8 papers, 2013 to 2024). A primary or metastatic malignant neoplasm involving the stomach. "In gastric cancer, inhibiting ALDH3A1 impairs mitochondrial activity due to reduced beta oxidation of lipids and acetyl co-A flux for TCA cycle, which was also demonstrated by our LC/MS analyses." (PMID 35707206, 2022). "We showed that blocking ALDH3A1 and mitochondrial complex I using gossypol and phenformin, respectively, had synergistic anti-cancer effects in a preclinical gastric cancer model." (PMID 31705020, 2019). "Here, we examined energy metabolism in gastric cancer cells and found increased fatty acid oxidation and increased expression of ALDH3A1." (PMID 31705020, 2019). "This suggests that fatty aldehydes are produced due to spontaneous peroxidation by ROS as an electron donor, which leads to generation of hydroxynonenoic acid (HNA) by ALDH3A1 for further downstream fatty acid oxidation (β-oxidation) in gastric cancer cells." (PMID 31705020, 2019). "To investigate the clinical significance of ALDH3A1 in gastric cancer, we analyzed expression of ALDH3A1 protein along with clinical outcomes using 1132 gastric cancer tissue samples in a TMA." (PMID 31705020, 2019). "Here, we found that about 40% of NADH produced by gastric cancer is dependent on ALDH3A1-mediated β-oxidation of fatty acids via conversion of fatty aldehydes to fatty acids." (PMID 31705020, 2019). "Knockdown of ALDH3A1 in gastric cancer cells inhibited cell growth by about 50–70% over 48 h." (PMID 31705020, 2019). "However, we found that gastric cancer cells expressed high levels of ALDH3A1, which correlated inversely with overall survival among those with ALDH isotypes other than ALDH1L1." (PMID 31705020, 2019). "The aim of this study is to investigate whether ALDH3A1 is a major contributor to ATP production via generation of NADH as an extra source of electrons in gastric cancer cells." (PMID 31705020, 2019). "Therefore, blockade of ALDH3A1 together with mitochondrial complex I using gossypol and phenformin led to significant therapeutic effects in a preclinical gastric cancer model." (PMID 31705020, 2019). "To test whether decreased expression of ALDH3A1 affects fatty acid oxidation, we measured β -oxidation by treating gastric cancer cells (in which ALDH3A1 was knocked down) with linoleic acid or oleic acid under fatty acid-restricted conditions." (PMID 31705020, 2019). "Among the isotypes of ALDH, stomach cancer cells showed increased expression of ALDH3A1." (PMID 31705020, 2019). "Besides their involvement in metabolizing exogenous substances through cytochrome P450 and drug metabolic pathways, ADH7, ALDH3A1, and ADH1B are also cross-genes with high connectivity within these pathways, indicating their potential use as diagnostic and prognostic biomarkers for gastric cancer." (PMID 39418180, 2024). "Therefore, targeting ALDH3A1 may have potential anti-cancer effects against gastric cancer." (PMID 31705020, 2019).
head and neck squamous cell carcinoma (7 papers, 2018 to 2025). A squamous cell carcinoma that arises from any of the following anatomic sites: lip and oral cavity, nasal cavity, paranasal sinuses, pharynx, larynx, and salivary glands. "Moreover, they showed that reduced ALDH3A1 expression enhanced the polarization and metastasis of tumor-associated neutrophils (TANs) in head and neck squamous cell carcinoma, and played a central role as a tumor suppressor and metabolic regulator." (PMID 40657474, 2025). "In head and neck squamous cell carcinoma (HNSCC) cells resistance to GSH depletion was driven by upregulation of aldehyde dehydrogenase 3A1 (ALDH3A1)." (PMID 31426306, 2019). "In head and neck squamous cell carcinoma, activation of ALDH3A1 increases chemoresistance against cisplatin whereas combining cisplatin with an ALDH inhibitor results in more pronounced cell viability reduction than treatment with each compound alone." (PMID 29854309, 2018). "Sulfasalazine-resistant head and neck squamous cell carcinoma (HNSCC) cells were found to highly express ALDH3A1 and knockdown of ALDH3A1 rendered these cells sensitive to sulfasalazine." (PMID 30333913, 2018). "Additionally, they determined that the ALDH3A1 expression was high in SAS-resistant head and neck squamous cell carcinoma (HNSCC) cells and that ALDH3A1 knockdown resulted in SAS sensitivity." (PMID 34502181, 2021).
oral squamous cell carcinoma (7 papers, 2017 to 2025). "Oral squamous cell carcinoma originates from genetic mutation in the upper layer of oral mucosa, and the high expression of ALDH3A1 in normal oral mucosal epithelium may be responsible for these adverse outcomes." (PMID 38191346, 2024). "ALDH3A1 acts as a prognostic biomarker and inhibits the epithelial–mesenchymal transition of oral squamous cell carcinoma through IL-6/STAT3 signaling pathway." (PMID 34928471, 2022). "Previous studies showed that oral squamous cell carcinoma with low ALDH3A1 expression was significantly worse than its high-ALDH3A1-expression counterpart, and its overexpression could drive cancer stem cell expansion and impair immune surveillance." (PMID 38791062, 2024). "A study reported another mechanism that IL-6/STAT3 pathway could be activated through ALDH3A1, contributing to reduced cell proliferation, migration, and invasion in oral squamous cell carcinoma 28, which was in consistent with our findings." (PMID 34234849, 2021). "To investigate the specific isoform of ALDH that may be responsible for the increased ALDH activity observed in the cisplatin-treated cells, we examined ALDH1A1, ALDH2 and ALDH3A1 expression at the protein level in primary oral cavity squamous cell carcinoma samples from patients." (PMID 28881734, 2017).
squamous cell carcinoma (7 papers, 2011 to 2025). A carcinoma arising from squamous epithelial cells. "Moreover, ALDH1A1 and ALDH3A1 exhibit elevated expression in squamous cell carcinoma and adenocarcinoma, and their upregulation may contribute to malignant transformation." (PMID 40868269, 2025). "In squamous cell carcinomas, it has been shown that SOX2 and P63 co-localize, interact, and co-regulate downstream genes such as ALDH3A1." (PMID 40643470, 2025). "ALDH3A1 is highly expressed in two types of NSCLC, adenocarcinoma and squamous cell carcinoma." (PMID 31534455, 2019). "Other recent work in humans demonstrated ALDH3A1 and ALDH1A1 expression by immunohistochemistry in squamous cell carcinomas (SSCAs) and adenocarcinomas (AdenoCAs), but not in small cell lung cancer (SCLC)." (PMID 21489244, 2011).
keratoconus (6 papers, 2013 to 2024). A degenerative, structural disorder of the eye, characterized by a cone-shaped protrusion of the cornea. "No 95% CS are defined here for CRF locus 11 (closest gene to lead variant EFEMP1) and locus 100 (closest gene ALDH3A1), the latter also a keratoconus GWAS locus." (PMID 37621707, 2023). "We showed that the rs1042183 variant in the ALDH3A1 gene is associated with a predisposition to keratoconus in the Polish population." (PMID 35011749, 2021). "In this study, we examined the potential role of ALDH3A1 variants as risk factors for keratoconus incidence and severity in a large group of Polish keratoconus patients." (PMID 35011749, 2021). "This downregulation of ALDH3A1 in cornea keratocytes under high curvature conditions may be associated with the stromal cloudiness observed in keratoconus." (PMID 38464213, 2024). "However, none of the genome-wide association studies has indicated that the ALDH3A1 locus is associated with keratoconus." (PMID 35011749, 2021). "Elevated ALDH3A1 levels were also observed in mouse injury models with increased corneal strain and keratoconus patients." (PMID 39652089, 2024). "The scRNA‐Seq revealed a significant increase in the expression levels of ALDH3A1 in keratocytes from keratoconus patients, while the expression level of IL‐8 demonstrated a decrease." (PMID 39652089, 2024). "Mouse injury models and single‐cell RNA sequencing of keratocytes from keratoconus patients were used to assess how strain influenced ALDH3A1 in vivo." (PMID 39652089, 2024). "Through single‐cell RNA sequencing analysis of keratocytes from keratoconus patients, we also confirmed the increased expression of ALDH3A1 and the decreased expression of IL‐8." (PMID 39652089, 2024). "Similarly, keratoconus patients exhibit prolonged elevation in corneal strain, and our results showed a significant upregulation of ALDH3A1 mRNA in keratocytes confirming a similar correlation as in our two mice models." (PMID 39652089, 2024). "ALDH3A1 is an important detoxifying enzyme in corneal epithelial cells comprising up to 40% of the soluble protein content of mammals and has been proposed to be involved in keratoconus aetiology." (PMID 35011749, 2021). "All of this indicates that ALDH3A1 is a determinant of the keratoconus pathology." (PMID 35011749, 2021). "At the first locus, the variant with the highest PIP in the solely FINEMAP-defined signal (rs4646785, intronic ALDH3A1, PIP = 0.26) forms the keratoconus credible set defined by all three fine-mapping methods (PIP >0.95)." (PMID 37621707, 2023).
glioma (5 papers, 2017 to 2023). A benign or malignant brain and spinal cord tumor that arises from glial cells (astrocytes, oligodendrocytes, ependymal cells). "The porcupine inhibitor LGK974 reduces Wnt signaling and decreased expression of ALDH3A1 mRNA and protein in glioma cells, thereby increasing their susceptibility to TMZ treatment." (PMID 29854309, 2018). "Additionally, our functional data suggest the utility of high ALDH3A1 expression as a putative diagnostic marker for stemness in glioma as indicated by reduced expression of CD133, Nestin and Sox2 as well as diminished clonogenicity in response to ALDH3A1 inhibition." (PMID 29854309, 2018). "In summary, our results reveal that ALDH3A1 expression in glioma cells can be modulated by Wnt pathway inhibition." (PMID 29854309, 2018). "A previous study reported that ALDH3A1 could modulate glioma proliferation and migration, whereas the other two genes have been poorly investigated." (PMID 35116021, 2021). "Our findings suggest that the enzyme ALDH3A1 might act as a therapeutic target whose inhibition sensitizes glioma cells to TMZ." (PMID 29854309, 2018). "Moreover, decreased overall cell viability following reduced ALDH3A1 expression could be due to the depletion of glioma cells with stem-like properties." (PMID 29854309, 2018). "We identified 8 plasma proteins which were increased in gliomas vs. meningiomas (GFAP, NEFL, EDDM3B, PROK1, MMP3, CTRL, GP2, SPINT3) and 4 proteins which were decreased in gliomas vs. meningiomas (FABP4, ALDH3A1, IL-12B and OXT)." (PMID 36959545, 2023). "Based on our scoring system, three out of five ALDHs (ALDH3A1, ALDH3B1 and ALDH16A1) were identified as unfavorable biomarkers for gliomas." (PMID 35116021, 2021). "In the LGG cohort from the TCGA dataset, ALDHs including ALDH2, ALDH6A1, ALDH5A1, ALDH9A1, ALDH1A1 were upregulated in WHO grade II gliomas while the increased expression of ALDH16A1, ALDH3B1, ALDH3A2, ALDH1A2, ALDH3A1 was found in WHO III grade gliomas." (PMID 35116021, 2021). "Analysis of the TCGA dataset showed that ALDH16A1, ALDH3B1, ALDH1A3, ALDH3A1, ALDH7A1 were significantly increased in IDH wildtype gliomas, while ALDH2, ALDH6A1, ALDH5A1, ALDH1A1, ALDH1L2, ALDH18A1, ALDH1B1 expression were higher in IDH mutant gliomas than IDH wildtype gliomas." (PMID 35116021, 2021). "To test whether ALDH3A1 mediates the resistance to TMZ, we created glioma cells with genetically down-regulated ALDH3A1 expression." (PMID 29854309, 2018). "Furthermore, we show that down-regulation of ALDH3A1 increases TMZ sensitivity and reduces stemness features in glioma cells in vitro independent of the MGMT promoter methylation status." (PMID 29854309, 2018).
hepatocellular carcinoma (5 papers, 2015 to 2025). A malignant tumor that arises from hepatocytes. "ALDH3A1 is overexpressed in a subset of hepatocellular carcinoma characterized by activation of the Wnt/β-catenin pathway." (PMID 27534621, 2016). "While ALDH3A1 is expressed at low levels in normal liver tissue, its expression is markedly upregulated in hepatocellular carcinoma (HCC)." (PMID 40722708, 2025).
lung adenocarcinoma (5 papers, 2019 to 2025). A carcinoma that arises from the lung and is characterized by the presence of malignant glandular epithelial cells. "In human lung adenocarcinoma cisplatin resistance cell line, ALDH3A1 was screened and might participate in tumor resistance." (PMID 34234849, 2021). "Additionally, when we analyzed the COX-2 expression in relation to ALDH3A1, we found 11 positive cases out of 13 (84.6%) for lung adenocarcinoma and six positive cases out of seven (85.7%) for skin melanoma, with high H scores for both ALDH3A1 and COX-2." (PMID 31817719, 2019).
gastric tumor (4 papers, 2018 to 2022). "The combination of dyclonine and sulfasalazine cooperatively suppressed the growth of highly ALDH3A1-expressing HNSCC or gastric tumors that were resistant to sulfasalazine monotherapy." (PMID 30333913, 2018). "In the present study, tumors formed by K19-Wnt1/C2mE-KP cells, which were established from a mouse gastric tumor, were also found to express ALDH3A1 at a high level and to be resistant to sulfasalazine treatment." (PMID 30333913, 2018). "While some ALDH family members are known to oxidize 4HNE and other aldehydes to their corresponding acids, only recently have ALDH3A1 and ALDH3A2 been recognized as being associated with ferroptosis resistance in head and neck cancers, gastric tumors, and leukemia cells." (PMID 36274088, 2022).